TLR4 (toll like receptor 4)
Diseases named in the same sentence as TLR4 in open-access papers (continued):
Sharing a sentence is not in itself a finding about the gene and the disease.
Sepsis (continued). "In line with findings for TLR4, MyD88, and NF-κB, sepsis significantly increased renal expression of NLRP3 and caspase-1 and its activated form (cleaved caspase-1 protein) compared to controls, as shown through Western blotting." (PMID 40869248, 2025). "Damage-associated molecular patterns (DAMPs) are endogenous molecules released from stressed or inflamed cells that induce aberrant immune responses, leading to organ injury via Toll-like receptor 4 (TLR4) in sepsis." (PMID 40421030, 2025). "Mechanistically, it mainly originates from the endothelium during sepsis, and TLR4-ERK signaling mediates the rapid secretion of METRNL via the classical ER-Golgi pathway in response to LPS stimulation." (PMID 40205457, 2025). "Multiple TLR4 inhibitors have been investigated as a means to improve outcomes from severe sepsis, but so far these approaches have been unsuccessful in clinical trials." (PMID 40463015, 2025). "During sepsis, activation of TLR4 in hepatocytes upregulates caspase-11 expression, thereby promoting hepatocyte pyroptosis and exosome release." (PMID 41252417, 2025). "Previous studies have also revealed that the related role of PI3K/Akt, ERK, TLR4/NF-κB, and HIF-1α involved in sepsis-associated inflammation and cardiac injury." (PMID 41311552, 2025). "Previous studies have shown that PCSK9 enhances TLR4/MyD88/NF-κB signaling and endothelial dysfunction during sepsis." (PMID 41462858, 2025). "In sepsis-induced myocardial injury models, H2S downregulates TLR4 and NLRP3 protein expression, inhibits MyD88-NF-κB signaling activation to reduce cytokine secretion, and blocks NLRP3 inflammasome assembly and IL-1β processing." (PMID 41277967, 2025). "The mechanism of action of LSECs in sepsis is complex and diverse, involving multiple aspects such as the TLR4 signaling pathway, PD-L1-mediated immune regulation, the secretion of cytokines like IL-6 and CXCL10, and the regulation of Tregs." (PMID 40072101, 2025). "For instance, eritoran, a TLR-4 antagonist, was initially designed to inhibit TLR4-mediated overactivation of the immune response in sepsis." (PMID 40404908, 2025). "Further, we found the expression level of TLR4 on monocytes was higher than that in aseptic inflammation and sepsis." (PMID 40084252, 2025). "Detecting p65 phosphorylation highlights the interplay between TLR4 signaling and inflammatory mechanisms in conditions such as sepsis, cancer, and chronic inflammation." (PMID 40244381, 2025). "MiR-217 can target TLR4 to modulate podocyte apoptosis, but the involvement of the miR-217/TLR4 axis in CASC7-regulated sepsis-induced liver injury is still unclear." (PMID 39067063, 2025). "This process contributes to systemic inflammation and sepsis progression, positioning TLR4 as a potential therapeutic target for modulating sepsis-associated inflammation." (PMID 40003683, 2025). "That study reveals that GAS5 acts as a sponge for miR-23a-3p, increasing the expression of TLR4 and thereby promoting inflammation and apoptosis in sepsis." (PMID 39941145, 2025). "A positive correlation with the activation of the JAK/STAT signaling pathway in sepsis and allergic contact dermatitis has been reported in TLR4 expression." (PMID 40005807, 2025). "Through bioinformatic analysis of the pediatric and adult sepsis datasets, we found that the gene expressions of TLR2 and TLR4 were significantly up-regulated in PBMC or blood samples of sepsis patients compared with the healthy controls." (PMID 40963927, 2025). "These LPS-driven effects are also partly due to the activation of TLR4/NF-κB interaction, since inhibition of this pathway improves sepsis-induced tissue injury." (PMID 40003683, 2025). "Overall, LPS-induced extracellular AREG aggravated or triggered macrophage pyroptosis through the EGFR/TLR4/Myd88/NF-κB signaling pathway, providing promising treatment strategies for sepsis." (PMID 40292295, 2025).
Sepsis (continued). "Future studies should focus on optimising delivery systems, exploring potential synergies with existing therapeutic regimens, and evaluating efficacy in related TLR4‐driven conditions such as sepsis‐induced acute respiratory distress syndrome (ARDS)." (PMID 41230791, 2025). "Based on these results, we suggest that minocycline helps the body by affecting sepsis-related brain inflammation, which is mainly controlled by microglia through TLR4-dependent pathways." (PMID 41142251, 2025). "Mechanistically, microbial translocation in sepsis results in the activation of hepatic Kupffer cells through TLR4 signaling, which triggers downstream NF-κB activation and induces the release of proinflammatory cytokines such as TNF-α and IL-1β." (PMID 41268545, 2025). "This phenomenon can result in resistance to TLR-4 inhibitors in cancer cells, analogous to the compensatory pathways activated during sepsis when TLR-4 is inhibited." (PMID 40404908, 2025). "In sepsis, TLR4/MD2 activation not only leads to systemic inflammatory response syndrome (SIRS) but also triggers immune paralysis, increasing the patient's susceptibility to secondary infections." (PMID 39976020, 2025). "As reported in our previous study, exogenous H2S inhibited inflammation and ERS by inhibiting the TLR4 pathway, thereby improving sepsis-induced heart dysfunction." (PMID 39907066, 2025). "For example, the impact of age-related changes in platelet TLR4 signaling or the role of comorbidities in exacerbating sepsis-induced thrombocytopenia should be examined." (PMID 40003683, 2025). "TLR2 and TLR4 are the most studied TLRs in sepsis, and selective targeting of these receptors using monoclonal antibodies has shown promise." (PMID 40386784, 2025). "and demonstrates anti-inflammatory properties by reducing pro-inflammatory cytokines, inhibiting NLRP3 inflammasome activation, and blocking TLR4/NF-κB signaling in various pathological contexts (e.g., sepsis, hyperhomocysteinemia)." (PMID 41277967, 2025). "Antagonists of TLR4 are molecules that function as inhibitors of TLR4 signalling pathways to treat endotoxemia, sepsis and septic shock." (PMID 41010682, 2025). "Mechanistically, these effects are attributed to the suppression of TLR4/NF-κB signaling, which is a critical pathway driving inflammatory responses in sepsis and other vascular pathologies." (PMID 40278266, 2025). "Together, our findings reveal a mechanism whereby ADAP resets macrophage function by controlling the TLR4-induced upregulation of PDPN as a host innate immune defense during sepsis." (PMID 39903516, 2025). "To confirm this, we analyzed the GEO database of pediatric and adult septic patient samples for the correlation of TLR2 and TLR4 expressions with the disease development and progression in sepsis." (PMID 40963927, 2025). "Overall, these findings suggest that APOH plays a protective role in sepsis by suppressing M1 polarization, at least partially, by inhibiting of the TLR4/NF-κB signalling pathway." (PMID 38291524, 2024). "Survival analysis indicated that Cmtm3 KO significantly improved the survival rate of CLP-induced sepsis mice, whereas TLR4 overexpression increased the mortality rate of Cmtm3 KO mice." (PMID 39455728, 2024). "Our data have clearly shown that eCIRP induces Kupffer cell M1 polarization via TLR4 pathway in sepsis, resulting in overproduction of inflammatory cytokines." (PMID 38881891, 2024). "Activation of the Toll-Like Receptor 4 (TLR4) signaling pathway is regarded as a critical component of sepsis, releasing pro-inflammatory mediators and reactive oxygen and nitrogen species." (PMID 39845954, 2024). "In monocytes from sepsis patients, acetylation of TLR4-TIR was significantly enhanced specially in CD16+ monocytes that had the potency to differentiate into M1 macrophages and acted as the major pro-inflammatory cells in the progression of sepsis." (PMID 39294473, 2024).
Sepsis (continued). "In our analysis, increased TLR4 expression was noted in sepsis patients, it was supposed that increase in CD14 expression should occur in LPS stimulated macrophages." (PMID 39294473, 2024). "Inflammatory signaling triggered by TLR4 during infection can lead to sepsis, septic shock, and death." (PMID 39452191, 2024). "Their data confirmed that inhibition of PCSK9 prevented TLR4 activation during sepsis, improved vascular function and increased survival in septic mice." (PMID 39736777, 2024). "During sepsis, the presence of LPS can trigger the TLR4 signaling pathway, leading to the translocation of NF-κB, subsequently impacting the expression of pro-inflammatory cytokines, such as IL-1β and interleukin-6 (IL-6)." (PMID 39677961, 2024). "Further to this, HMGB1 is an extracellular molecule that triggers inflammatory responses under conditions such as sepsis and myocardial infarction and carries out its biological role through its receptor TLR4." (PMID 38256928, 2024). "RKH binds to TLR4 directly and inhibits TLR4 activation in immune cells, preventing organ damage and death brought on by sepsis." (PMID 38685971, 2024). "The cold-inducible RBP, CIRP, induces inflammatory responses in hemorrhagic shock and sepsis and activation of splenic T cells dependent on the TLR4." (PMID 38727856, 2024). "The toll-like receptor 4 (TLR4) receptor plays an important role in regulating the innate immune response to bacterial infection during sepsis." (PMID 38549133, 2024). "The mean serum levels of TNF-α, MIF, TLR4, and 8-epi-PGF2α levels were significantly higher in the sepsis and vehicle groups than in the normal and sham groups." (PMID 39144689, 2024). "In sepsis patients, significantly elevated TLR4-TIR acetylation is observed in CD16+ monocytes combined with elevated expression of M1 macrophage markers." (PMID 39294473, 2024). "The literature indicates that TLR4 plays a crucial role in neutrophil migration during sepsis, influencing neutrophil movement through the regulation of CXCR2 expression." (PMID 39455728, 2024). "In LPS‐treated rats, ferrostatin‐1 ameliorates sepsis‐induced cardiac dysfunction and dramatically lowers TLR4, NF‐κB, and IκBα levels." (PMID 38685971, 2024). "Further, we extracted peripheral blood mononuclear cells in sepsis patients and found a significant increase in both Rab5a and cell surface TLR4 expression compared with Health volunteers." (PMID 38549133, 2024). "Serum TLR4 levels were also significantly elevated in the sepsis and vehicle groups compared to the normal and sham groups." (PMID 39144689, 2024). "The Xijiao Dihuang decoction ameliorates sepsis prognosis by curbing glycolysis, achieved through the inhibition of TLR4 and its downstream signaling pathways." (PMID 39712019, 2024). "miR-22 alleviates sepsis-induced acute kidney injury via targeting the HMGB1/TLR4/NF-κB signaling pathway." (PMID 38443846, 2024). "Histopathological analysis of liver, lung, and kidney tissues using HE stains revealed that Cmtm3 KO reduced the pathological injury in these organs in CLP-induced sepsis mice, while TLR4 overexpression reversed this effect." (PMID 39455728, 2024). "Therapeutic approaches that reduce NET formation, such as peptidylarginase deaminase 4 and TLR4 inhibitors, can improve lung injury and attenuate inflammation in sepsis." (PMID 38921594, 2024). "The overactivation of the TLR4 signaling pathway is a common feature in sepsis, and controlling its expression is considered key to regulating neutrophil activity." (PMID 39455728, 2024). "To further explore the role of TLR4-TIR acetylation in sepsis, we initially isolated TLR4-TIR-acetylated cells from the PBMCs enriched monocytes of sepsis patients using the specific TLR4 acetylation antibody." (PMID 39294473, 2024).
Sepsis (continued). "We note, however, that LPS studies cannot fully represent the dynamics of sepsis since LPS stimulates the toll‐like receptor 4 (TLR‐4) pathway, whereas inflammation during sepsis can be stimulated via multiple pathways." (PMID 38466166, 2024). "In particular, after recognizing LPS, TLR4 activates the NF-κB and MAPK signaling pathways, initiating a pro-inflammatory response that further triggers the sepsis-associated inflammatory cascade." (PMID 39720715, 2024). "Let-7b has been found to inhibit pro-inflammatory responses, especially IL-6 and TNF, by suppressing the TLR4/NFkB pathway in a mouse model of sepsis." (PMID 38400048, 2024). "TLR2 and TLR4 play a significant role in the recognition of these pathogens and the subsequent release of inflammatory cytokines during sepsis." (PMID 38835761, 2024). "In light sepsis in humans, an acute inflammatory response inducing the TLR4 pathway and inflammatory cytokine production is beneficial, but in severe sepsis these components are dysregulated, preventing inflammatory cytokine production by the PBMCs." (PMID 38658362, 2024). "In this study, we demonstrated for the first time, that propofol, acting as an immunomodulating agent, exerts its anti-inflammatory role in sepsis by targeting Rab5a and thereby downregulating membrane TLR4 expression by macrophages." (PMID 38549133, 2024). "Subsequently, we investigated the impact of CBP inhibitor and HDAC1 inhibitor on the progression of LPS-induced sepsis by intraperitoneally injecting TLR4-WT mice with SGC-CBP30, TSA, and HDAC1 inhibitor RG2833." (PMID 39294473, 2024). "Secreted human tryptophanyl-tRNA synthetase 1 (WARS1), an endogenous ligand for Toll-like receptor (TLR) 2 and TLR4 against infection, activates the genes that signify the hyperinflammatory sepsis phenotype." (PMID 38177528, 2024). "It was observed that CBP was significantly enriched in the cytoplasm of macrophages isolated from sepsis patients, suggesting its potential role in promoting high levels of TLR4-TIR acetylation in human CD16 + M1 macrophages." (PMID 39294473, 2024). "Activation of the Toll-like receptor 4 (TLR4) by bacterial endotoxins in macrophages plays a crucial role in the pathogenesis of sepsis." (PMID 39294473, 2024). "Sepsis is a potential outcome that can result from excessive and uncontrolled pro-inflammatory signaling triggered by toll-like receptor 4 (TLR4)." (PMID 39459616, 2024). "In conclusion, these findings suggest that during sepsis, TLR4 mediates the endocytosis of CIRP, thereby initiating this process in MPVECs through a dynamin-dependent pathway." (PMID 39465383, 2024). "Cmtm3 KO reduced the release of TNF-α, IL-1β, and IL-10 in the peripheral blood of CLP-induced sepsis mice, while TLR4 overexpression reversed this protective effect." (PMID 39455728, 2024). "It has been established that TLR2 and TLR4 are critically involved in the sepsis-induced depletion of splenic DCs." (PMID 38816685, 2024). "For instance, provoking innate immunity by toll-like receptor 4 (TLR4) or TLR7/8 agonists has been shown to enhance survival to polymicrobial sepsis in mice during neonatal life." (PMID 39340014, 2024). "Chlorthalidomide mitigates sepsis‐induced oxidative stress, mitochondrial structural damage and dysfunction, and cardiomyocyte apoptosis by controlling macrophage polarization via TLR4/NF‐κB/MAPK signaling." (PMID 38685971, 2024). "Crucially, it has been demonstrated that Sema3A interact with TLRs, particularly TLR4, to start the cytokine storm that is triggered by sepsis." (PMID 38756232, 2024). "Serum TLR4 levels were significantly higher in the sepsis group compared to the normal and sham groups (P <0.001)." (PMID 39144689, 2024). "In mice with endothelial cells lacking TLR4, pulmonary neutrophil recruitment is significantly reduced after exposure to LPS, illustrating the importance of alveolar endothelial TLR4 expression in pulmonary neutrophil recruitment during sepsis." (PMID 38835761, 2024).
Sepsis (continued). "Plenty of drugs, natural or artificial, were proved their protection effect on sepsis mouse models through inhibiting the activation of inflammatory cytokines via various signal pathways such as TLR4/NF-κB, MD-2/TLR4, ROS/NLRP3 pathways." (PMID 39267971, 2024). "Understanding the TLR4/NF-κB signaling transduction pathway is crucial for diagnosing and treating sepsis and S-AKI." (PMID 39459616, 2024). "In contrast, the ghrelin-treated group had significantly lower serum levels of TLR4 compared to the vehicle and sepsis group." (PMID 39144689, 2024). "TLR4 serves as the primary identifier of sepsis induced by LPS, triggering downstream NF-κB and IFN pathways through the activation of MyD88 and TRIF." (PMID 39267971, 2024). "In future work, co-administering Rosuvastatin and the TLR4/NF-κB axis agonist into the sepsis mice will be performed to identify the protection mechanism of Rosuvastatin against sepsis involving the TLR4/NF-κB axis." (PMID 38885061, 2024). "Previous studies have demonstrated that S100A12 enhances the expression of adhesion factors and induces the activation of human monocytes via Toll-like receptor 4, thereby acting as an enhancer of innate immunity in the early stages of inflammation and sepsis." (PMID 38238762, 2024). "Malfunctioning TLR4 signaling can inadvertently amplify immune responses, thereby inducing conditions like sepsis, acute lung injury, and pathological chronic inflammation, often linked to cancer and autoimmune maladies." (PMID 39294631, 2024). "TAK-242 is a molecular inhibitor of TLR4 that was developed to treat sepsis by inhibiting TLR4 signaling, thereby suppressing the excessive immune responses." (PMID 39056754, 2024). "Although blocking TLR4 can result in the protection of wild-type mice from lethal endotoxemia and lethal E. coli induced sepsis, TLR4 inhibitors and inflammatory cytokine antagonists do not meet the expectations in clinical trials as anti-sepsis drugs." (PMID 37049646, 2023). "Recent studies have found that the TLR4 pathway is involved in the inflammatory state of sepsis and can affect the expression of inflammatory cytokines induced by LPS in sepsis." (PMID 38102579, 2023). "We have clarified the effect of Triad3A on TLR4 regulation and mycobactericidal activity in the state of sepsis." (PMID 37506157, 2023). "In conclusion, J147 ameliorated the sepsis-induced depressive-like behaviors induced by neuroinflammation through attenuating the TLR4/NF-κB signaling pathway in microglia." (PMID 37676534, 2023). "All these results showed that DMB rescued mice from LPS-induced acute sepsis by inhibiting TLR4–MD-2 signaling." (PMID 37168866, 2023). "A recent study revealed that sepsis-derived S100A8/A9 induces GSDMD-dependent platelet pyroptosis in severe sepsis by upregulating the TLR4/NLRP3 signaling pathway, which leads to the release of oxidized mtDNA and promotes NETs formation." (PMID 37275856, 2023). "Compared to the sham group, the sepsis group had significantly elevated levels of TLR-4, IL-6, TNF-α, MIF, F2-isoprostane, caspase-3, cTn-I, and CK-MB (p<0.05)." (PMID 37900081, 2023). "In this review we describe the role of TLR4, its endogenous ligands and activation in the inflammatory response to ischemic/reperfusion-induced AKI and sepsis-associated AKI." (PMID 36674930, 2023). "In the last few years, most research was performed on TLR4 because of the importance of its ligand LPS in mediating sepsis, a worldwide public health issue." (PMID 36926280, 2023). "In sepsis, corilagin was shown to ameliorate an inflammatory response through the toll-like receptor 4 (TLR4)." (PMID 36829609, 2023). "This work establishes unambiguously that systemic hyperinflammtion upon infection was aggrevated by the loss of CD4+ T cells, that unleashed the restrains of MHC II/TLR4 inflammatory "signalosome" for cytokine storm or cytokine release syndrome in sepsis." (PMID 37332010, 2023).